NPAS4 (neuronal PAS domain protein 4)
Description:
Transcription factor expressed in neurons of the brain that regulates the excitatory-inhibitory balance within neural circuits and is required for contextual memory in the hippocampus (By similarity). Plays a key role in the structural and functional plasticity of neurons (By similarity). Acts as an early-response transcription factor in both excitatory and inhibitory neurons, where it induces distinct but overlapping sets of late-response genes in these two types of neurons, allowing the synapses that form on inhibitory and excitatory neurons to be modified by neuronal activity in a manner specific to their function within a circuit, thereby facilitating appropriate circuit responses to sensory experience (By similarity). In excitatory neurons, activates transcription of BDNF, which in turn controls the number of GABA-releasing synapses that form on excitatory neurons, thereby promoting an increased number of inhibitory synapses on excitatory neurons (By similarity). In inhibitory neurons, regulates a distinct set of target genes that serve to increase excitatory input onto somatostatin neurons, probably resulting in enhanced feedback inhibition within cortical circuits (By similarity). The excitatory and inhibitory balance in neurons affects a number of processes, such as short-term and long-term memory, acquisition of experience, fear memory, response to stress and social behavior (By similarity). Acts as a regulator of dendritic spine development in olfactory bulb granule cells in a sensory-experience-dependent manner by regulating expression of MDM2 (By similarity). Efficient DNA binding requires dimerization with another bHLH protein, such as ARNT, ARNT2 or BMAL1. Can activate the CME (CNS midline enhancer) element.
Synonyms: bHLHe79; NXF; PASD10; Le-PAS
Tractability: PROTAC: UniProt records ubiquitination sites on it.
Gene: Protein-coding gene on chromosome 11 (66,421,035 to 66,426,707, forward strand). Ensembl gene ENSG00000174576.
Subcellular location: Nucleus
Subcellular location (Human Protein Atlas): Nuclear bodies; Nucleoplasm; Nuclear membrane; Vesicles
Pathways (Reactome):
Gene expression (Transcription): NPAS4 regulates expression of target genes; Regulation of NPAS4 gene transcription; Regulation of NPAS4 mRNA translation
Gene Ontology:
Molecular function: DNA-binding transcription activator activity, RNA polymerase II-specific; DNA-binding transcription factor activity, RNA polymerase II-specific; protein binding; protein heterodimerization activity; RNA polymerase II cis-regulatory region sequence-specific DNA binding; RNA polymerase II transcription regulatory region sequence-specific DNA binding; protein dimerization activity; protein-containing complex binding
Biological process: positive regulation of transcription by RNA polymerase II; excitatory postsynaptic potential; inhibitory postsynaptic potential; inhibitory synapse assembly; learning; long-term memory; regulation of synaptic plasticity; regulation of synaptic transmission, GABAergic; regulation of transcription by RNA polymerase II; short-term memory; social behavior
Cellular component: chromatin; cytosol; nucleoplasm; nucleus; transcription regulator complex; postsynapse
Genetic constraint (gnomAD): Loss-of-function variants: 8 observed, 61.55 expected, observed/expected ratio (o/e) 0.13, 90% interval 0.075 to 0.23. The upper end of that interval is the gene's LOEUF score, 0.23, which puts it in group 1 of 6, group 1 being the genes least tolerant of losing a copy. Missense variants: 873 observed, 1,016.6 expected, observed/expected ratio (o/e) 0.86, 90% interval 0.81 to 0.91. Synonymous variants: 438 observed, 425.41 expected, observed/expected ratio (o/e) 1.03, 90% interval 0.95 to 1.11.
Homologues: Orthologues: chimpanzee NPAS4 (99% identical), macaque NPAS4 (99% identical), dog NPAS4 (96% identical), pig NPAS4 (94% identical), rabbit NPAS4 (94% identical), guinea pig NPAS4 (94% identical), rat Npas4 (93% identical), mouse Npas4 (93% identical), zebrafish npas4a (47% identical), tropical clawed frog npas4 (44% identical), zebrafish npas4b (30% identical), Drosophila melanogaster dysf (21% identical), and 1 more. Paralogues in human: EPAS1 (17% identical), HIF1A (17% identical), NPAS3 (16% identical), HIF3A (15% identical), SIM2 (15% identical), SIM1 (14% identical), NPAS1 (13% identical).
Diseases named in the same sentence as NPAS4 in open-access papers:
NPAS4 is named in the same sentence as 65 diseases in open-access papers, as found by Europe PMC text mining. Sharing a sentence is not in itself a finding about the gene and the disease. The quoted sentences say what the papers report.
Anxiety (19 papers, 2011 to 2025). Intense feelings of nervousness, tension, or panic often arise in response to interpersonal stresses. "In contrast, Npas4 expression is upregulated in focal cerebral ischemia, and Npas4-deficient mice display altered anxiety and social behavior following focal cortical stroke." (PMID 40715999, 2025). "A decreased expression of neuron PAS domain protein 4 (NPAS4) in the HIP has been associated with anxiety and depression-like behaviors." (PMID 40565663, 2025). "It has been reported that decreased expression of Npas4 in the hippocampus is associated with depression and anxiety, and that rats with higher Npas4 expression are more stress tolerant." (PMID 35889906, 2022). "Previous studies have shown that Npas4 KO mice have reduced anxiety, and that Npas4 heterozygous mice have increased depression-like behavior in the forced swim test." (PMID 36780219, 2023). "Following single prolonged stress, inhibition of miR-142-5p resulted in decreased anxiety-like behaviors and memory deficits, as well as increased expression of Npas4 and BDNF." (PMID 36979479, 2023). "Since decreased expression of Npas4 has been reported to result in anxiety and depression-like behavior, the effects of ingesting green tea components were compared." (PMID 35889906, 2022). "Thus, our findings suggest that the behavioral alterations in female mice with a history of MS (i.e., greater anxiety and enhancement of social behavior) may be associated with the level of Npas4 expression and subsequent changes in the expression of its target genes." (PMID 32190129, 2020). "However, Atg7 knockdown in the Fos-dependent robust activity marking ensemble promoted memory generalization, while knockdown of Atg5 or Atg7 in the Npas4-dependent robust activity marking ensemble increased anxiety levels." (PMID 40536998, 2025). "Several studies have suggested that NPAS4 may regulate depression, anxiety, and neurocognitive disorders and play a critical role in the correlation between long-term stress and symptoms of depression." (PMID 38461185, 2024). "Other animal models have indicated that NPAS4 could have a role in fear memory, anxiety, social- and depressive-like behavior and Npas4 knockout mice display social anxiety, hyperactivity, memory and learning deficits." (PMID 37938766, 2024). "Moreover, the presence of CSDS-induced social avoidance and anxiety-related behavior in Npas4 shRNAPFC mice argues against the possibility that they are simply less sensitive to stress and/or have deficits in threat/fear-related learning and memory." (PMID 36780219, 2023). "Alternatively, SST-specific Npas4-KO mice exhibited relatively minor anxiety-like behavior, which indicated that NPAS4 might also act as a harmful factor." (PMID 37176030, 2023). "Interestingly, our previous work revealed that Npas4 is epigenetically regulated in a conditional Tet3 KO mouse model that presents anxiety-like behavior and cognitive deficits." (PMID 32848656, 2020). "Our goal was to investigate the effects of a deregulation of the inhibitory pathways caused by the absence of the transcription factor Npas4 on locomotor activity, anxiety, sensorimotor gating, social and cognitive behaviors." (PMID 23029555, 2012). "In contrast, somatostatin-expressing GABAergic neuron-specific knockout of Npas4 in CA1 alters synaptic transmission in these neurons, increases activity in pyramidal neurons, and reduces anxiety behavior." (PMID 40715999, 2025). "Another similar paradigm supported the idea of social anxiety in mice lacking Npas4: when Npas4-KO mice faced an unfamiliar male conspecific in a neutral environment, they spent more time avoiding contact with the conspecific than the WT." (PMID 23029555, 2012). "Furthermore, in mice lacking NPAS-4 after ischemic stroke, increased anxiety levels and impairments in social behavior have been observed." (PMID 40563435, 2025).
Anxiety (continued). "On day 7, in mice treated with nepicastat, there was an increase of Npas4 and Bdnf mRNA expression in the hippocampus.In conclusion, DBH inhibitor nepicastat has an effect consistent with a decrease in the persistence of traumatic memories and anxiety-like behavior in this PTSD mice model." (PMID 34630037, 2021). "Interestingly, NPAS4 is not required for CSDS-induced social avoidance or anxiety-like behavior." (PMID 36780219, 2023). "However, mice lacking Npas4 displayed another form of anxiety: social anxiety." (PMID 23029555, 2012). "However, mPFC NPAS4 was not required for CSDS-induced social avoidance or anxiety-like behavior, suggesting that CSDS produces those phenotypes through distinct molecular and/or circuit mechanisms devoid of NPAS4 function." (PMID 36780219, 2023).
depression (16 papers, 2014 to 2025). "NPAS4 has been proposed as a therapeutic target not only for depression and neurodegenerative diseases associated with synaptic dysfunction but also for type 2 diabetes and pancreas transplantation." (PMID 29899116, 2018). "Our study suggests the central role of NPAS4 in major depression as an association factor." (PMID 38062059, 2023). "NPAS4 has been proposed as a novel therapeutic target for depression and neurodegenerative diseases associated with synaptic dysfunction, as a component of new stroke therapies, as a therapeutic target for diabetes, and as a treatment during pancreas transplantation." (PMID 29899116, 2018). "Besides, the actual literature describes some of the genes (RORA, Gabrb2, Npas4, and Junb) being associated with depression-like behavior." (PMID 25400562, 2014). "In depression models, a decrease in NPAS-4 expression, particularly in the hippocampal region, has been demonstrated, and this reduction has been associated with mood regulation." (PMID 40563435, 2025). "In human studies, significantly lower levels of NPAS-4 have been found in peripheral blood mononuclear cells of patients with post-stroke depression." (PMID 40563435, 2025). "Another member of the family, expressed mainly in the brain, neuronal PAS domain-containing protein 4 (NPAS4) has been proposed as a novel therapeutic target for depression and neurodegenerative diseases and as a component of new stroke therapies." (PMID 31357385, 2019). "Much of this work has been done in HPC, and further studies are needed to characterize the role of NPAS4 in NAc and other reward circuitry areas in the context of the same depression models." (PMID 28503137, 2017). "Relative hippocampal Npas4 expression was significantly lower in a rat depression model compared to controls." (PMID 25400562, 2014). "Compared with the control group, hippocampal NPAS4 mRNA levels were significantly lower in the simple depression (P<0.01) and PSD groups (P<0.05)." (PMID 24669275, 2014). "The PSD rats displayed neuropsychopathic disorders and the NPAS4 mRNA expression levels in the hippocampus were significantly lower in the depression and PSD groups compared with the control group." (PMID 24669275, 2014). "Notably, lack of NPAS4 and/or BDNF expression has been linked to neurodegenerative diseases and worsened disease stroke/ischemia models and reductions of both Npas4 and Arnt2 mRNA have been observed in a rat model of depression." (PMID 30231889, 2018). "Npas4 belongs to the bHLH-PAS family of transcription factors and the other Npas members (1 and 3) are also linked to numerous psychiatric disorders namely autism, bipolar disorders, schizophrenia and depressive disorders." (PMID 29915698, 2018). "For other IEGs, such as Egr-1, NPAS4, and Arc, their induction by stress makes them molecules of interest in mood disorder research, but causal connections to depression-related behaviors have not yet been uncovered, and continued study of their role in reward circuitry function is needed." (PMID 28503137, 2017). "(F) Overlap of significantly differential expression genes (p<0.05) in Npas4 shRNAPFC mice (left; blue) and differential expression genes (p<0.05) in BA8/9 of human major depressive disorder (MDD) patients (right; pink)." (PMID 36780219, 2023). "Future strategies targeting these Npas4-regulated pathways could be a novel approach to develop therapeutic treatments for hypofrontality and anhedonia-related symptoms in patients struggling with depression, bipolar disorder, and other stress-related neuropsychiatric disorders." (PMID 36780219, 2023). "Moreover, the majority (66.2%) of the Npas4 shRNA-downregulated genes from our analysis overlapped with upregulated genes in human MDD patients, suggesting that Npas4 expression could contribute to vulnerability to depression in the human brain." (PMID 36780219, 2023).
epilepsy (13 papers, 2014 to 2025). A brain disorder characterized by episodes of abnormally increased neuronal discharge resulting in transient episodes of sensory or motor neurological dysfunction, or psychic dysfunction. "In addition, Npas4 is also implicated in protection against several neurological disorders or downstream sequela, including cerebral ischemia and epilepsy, both of which are associated with altered excitatory–inhibitory balance." (PMID 33335473, 2020). "Genes differentially expressed in human TLE samples and previously implicated in epilepsy (XIRP1, CCL2, and NPAS4), were predicted to have potential methylation sites and showed inverse expression changes to those found for snoRNAs in human TLE." (PMID 39509000, 2024). "In vivo studies in rodent models have shown that NPAS4 has a neuroprotective role in cerebral ischemia and epilepsy." (PMID 37938766, 2024). "The neuron protective activity of Npas4 is also considered in neuronal diseases including ischemic stroke and epilepsy." (PMID 34675183, 2021). "As a recent achievement in this regard, it was reported that Npas4 controls neuronal homeostasis in epilepsy through the induction of Homer 1a, and Npas4 also as one of pivotal transcriptional target of Hdac3-mediated repression in neurodegenerative disease." (PMID 33335473, 2020). "In our study, Npas4 protein expression was investigated in the hippocampi and adjacent neocortices of pilocarpine-induced epilepsy rats." (PMID 25536221, 2014). "Additional research should investigate how Npas4 regulates the GABAergic synapse to inhibit epilepsy." (PMID 25536221, 2014). "In the epilepsy rat model, double-label immunofluorescence staining showed that Npas4 and MAP2 were co-expressed in neurons in the cortex and hippocampus but were not co-expressed with GFAP, an astrocyte marker, in neuroglia cells in the hippocampus and cortex." (PMID 25536221, 2014). "The mechanisms of Npas4 responsible for protecting against epilepsy may regulate GABAergic synapse development through the transcriptional regulation of BDNF." (PMID 25536221, 2014). "Downregulated miR-744 could downregulate Npas4 as an intrinsic regulator of seizures and epilepsy." (PMID 37133759, 2023). "Notably, upregulation of NOVA1, neuroLSD1, and of the IEG proteins NR4A1, EGR1, and NPAS4 has been observed in patients with epilepsy and/or in epileptic mouse models, and their deregulation might contribute to DEE9 epileptic phenotype." (PMID 35613587, 2022). "Npas4 may play an important role in the pathogenesis of epilepsy." (PMID 25536221, 2014). "Furthermore, Npas4 may act as a molecular switch to initiate homeostatic scaling in the hippocampus, a function that suggests new therapeutic approaches for the treatment of epilepsy." (PMID 33335473, 2020). "Therefore, Npas4 may participate in the pathogenesis of epilepsy." (PMID 25536221, 2014). "However, it is still unknown whether Npas4 participates in the pathogenesis of epilepsy." (PMID 25536221, 2014). "Because of the ethical and experimental conditions, we have not detected the expression of Npas4 in the brain tissue of patients with epilepsy." (PMID 25536221, 2014). "Although several studies have suggested that Npas4 may be related to seizures and psychiatric disorders, the exact mechanism by which Npas4 participates in the inhibitory pathway and leads to the symptomatology of developmental disorders, such as epilepsy, has not been fully determined." (PMID 25536221, 2014).